AP1AR (adaptor related protein complex 1 associated regulatory protein)
Description:
Necessary for adaptor protein complex 1 (AP-1)-dependent transport between the trans-Golgi network and endosomes. Regulates the membrane association of AP1G1/gamma1-adaptin, one of the subunits of the AP-1 adaptor complex. The direct interaction with AP1G1/gamma1-adaptin attenuates the release of the AP-1 complex from membranes. Regulates endosomal membrane traffic via association with AP-1 and KIF5B thus linking kinesin-based plus-end-directed microtubular transport to AP-1-dependent membrane traffic. May act as effector of AP-1 in calcium-induced endo-lysosome secretion. Inhibits Arp2/3 complex function; negatively regulates cell spreading, size and motility via intracellular sequestration of the Arp2/3 complex.
Synonyms: GBAR; Gamma-BAR; C4orf16; PRO0971; 2C18
Tractability: PROTAC: ubiquitination databases record sites on it; its protein half-life has been measured.
Gene: Protein-coding gene on chromosome 4 (112,231,363 to 112,273,110, forward strand). Ensembl gene ENSG00000138660.
Subcellular location: Golgi apparatus, trans-Golgi network; Late endosome; Early endosome
Subcellular location (Human Protein Atlas): Golgi apparatus
Gene Ontology:
Molecular function: AP-1 adaptor complex binding; kinesin binding
Biological process: Golgi to endosome transport; negative regulation of receptor recycling; negative regulation of substrate adhesion-dependent cell spreading; negative regulation of cell motility; regulation of Arp2/3 complex-mediated actin nucleation
Cellular component: Golgi apparatus; transport vesicle; endosome; cytosol; early endosome; late endosome
Genetic constraint (gnomAD): Loss-of-function variants: 15 observed, 22.04 expected, observed/expected ratio (o/e) 0.68, 90% interval 0.45 to 1.05. The upper end of that interval is the gene's LOEUF score, 1.05, which puts it in group 4 of 6, group 1 being the genes least tolerant of losing a copy. Missense variants: 222 observed, 234.1 expected, observed/expected ratio (o/e) 0.95, 90% interval 0.85 to 1.06. Synonymous variants: 90 observed, 80.98 expected, observed/expected ratio (o/e) 1.11, 90% interval 0.94 to 1.32.
Homologues: Orthologues: chimpanzee AP1AR (99% identical), macaque AP1AR (99% identical), dog AP1AR (97% identical), rabbit AP1AR (95% identical), guinea pig AP1AR (92% identical), mouse Ap1ar (90% identical), rat Ap1ar (90% identical), pig AP1AR (85% identical), tropical clawed frog ap1ar (62% identical).
Diseases named in the same sentence as AP1AR in open-access papers:
AP1AR is named in the same sentence as 5 diseases in open-access papers, as found by Europe PMC text mining. Sharing a sentence is not in itself a finding about the gene and the disease. The quoted sentences say what the papers report.
lung adenocarcinoma (1 paper, 2026). A carcinoma that arises from the lung and is characterized by the presence of malignant glandular epithelial cells. "AP1AR was consistently upregulated in lung adenocarcinoma and independently associated with poorer overall survival." (PMID 41438582, 2026).
lung carcinoma (1 paper, 2026). "In conclusion, our integrated multi-omics and single-cell analyses identify AP1AR as the most consistent AP-1 adaptor signal in lung cancer, with the strongest evidence in adenocarcinoma." (PMID 41438582, 2026). "Quantitative summaries confirmed decreased pathway activity and reduced ligand-receptor diversity, highlighting AP1AR expression as a key determinant of intercellular signaling intensity in lung cancer." (PMID 41438582, 2026). "Notably, AP1AR (adaptor protein complex 1-associated regulatory) has not been characterized in lung cancer or other solid tumors, representing an opportunity to explore novel mechanisms of tumor regulation." (PMID 41438582, 2026). "Overall, these converging multi-omics findings highlight AP1AR and AP1S3 as the most clinically relevant AP-1 adaptors in lung cancer, elucidating their roles in proliferation, stress adaptation, immune modulation, and drug response." (PMID 41438582, 2026). "A systematic multi-omics analysis was conducted for the eight AP-1 adaptor complex genes (AP1AR, AP1B1, AP1G1, AP1G2, AP1M1, AP1M2, AP1S1, and AP1S3) to characterize their roles in lung cancer." (PMID 41438582, 2026). "Unlike other AP-1 adaptor family members, AP1AR has not, to our knowledge, been functionally characterized in lung cancer; nevertheless, external resources document variable tumor protein detection, which aligns with our IHC observations." (PMID 41438582, 2026). "Importantly, AP1AR has not previously been characterized in lung cancer, highlighting its novelty and potential clinical value." (PMID 41438582, 2026). "CRISPR dependency screening confirmed that AP1AR moderately contributes to the fitness of lung-cancer cells, implying a non-redundant role in growth maintenance, and these interpretations are supported by the robustness and cross-study concordance of modern CRISPR dependency resources." (PMID 41438582, 2026).
tumor (1 paper, 2026). "AP1AR was primarily linked to cell-cycle regulation and DNA replication checkpoints, suggesting a role in sustaining tumor proliferation." (PMID 41438582, 2026). "In contrast, AP1AR-low tumors displayed globally reduced communication densities and weaker cross-lineage connectivity, with the most pronounced loss observed in fibroblast-to-epithelial and immune-to-tumor signaling." (PMID 41438582, 2026). "AP1AR shows transcriptional upregulation, independent associations with survival, promoter hypomethylation, enrichment of proliferation and epithelial to mesenchymal transition programs, and localization to tumor-driving cell types with altered stromal communication when low." (PMID 41438582, 2026). "GSEA and MetaCore analyses implicated AP1AR in cell-cycle progression, DNA-replication checkpoints, hypoxia, and EMT hallmark processes of tumor aggressiveness." (PMID 41438582, 2026). "Integration with clinical annotations showed higher AP1AR and AP1S3 expression in advanced-stage tumors and smoker-associated samples compared to non-tumor tissues, suggesting a link to aggressive disease phenotypes." (PMID 41438582, 2026). "Conversely, AP1AR-low tumors displayed diminished intercellular connectivity, particularly in fibroblast-to-epithelial and immune-to-tumor signaling, consistent with a dampened paracrine landscape." (PMID 41438582, 2026). "Protein-level validation via IHC confirmed detectable AP1AR in tumor tissues, aligning with transcriptional and functional findings." (PMID 41438582, 2026). "We additionally observed marked promoter hypomethylation in tumor samples, supporting an epigenetic mechanism for AP1AR activation." (PMID 41438582, 2026). "At the mechanistic level, CellChat modeling indicated that AP1AR-high tumors exhibit a communication-intensive tumor microenvironment, with fibroblast and epithelial populations acting as signaling hubs for immune and stromal interactions." (PMID 41438582, 2026). "The AP1AR-high group exhibited markedly enhanced intercellular communication within the tumor microenvironment (TME)." (PMID 41438582, 2026). "To investigate how AP1AR influences tumor-stromal interactions, we performed CellChat analysis, stratifying tumors by AP1AR expression." (PMID 41438582, 2026). "These interactions were enriched in growth factor- and cytokine-mediated pathways, including TGFB1-TGFBR2, IL6-IL6R, and EGF-EGFR signaling, suggesting that AP1AR upregulation amplifies paracrine networks supporting tumor proliferation and immune remodeling." (PMID 41438582, 2026). "Single-cell analyses localized AP1AR to malignant epithelial clusters enriched in proliferative phases, providing strong evidence that it may act directly within tumor-driving cell types." (PMID 41438582, 2026). "Pathological stage-specific analyses revealed progressive upregulation of AP1AR and AP1S3 with advancing tumor stage, whereas AP1S1 expression remained relatively stable." (PMID 41438582, 2026). "AP1AR was strongly enriched in pathways related to EMT, hypoxia, inflammatory response, and cell-cycle progression, highlighting its role in proliferation and tumor aggressiveness." (PMID 41438582, 2026). "CRISPR dependency screens indicated that AP1AR contributes to LUAD cell fitness, supporting a non-redundant role in tumor maintenance." (PMID 41438582, 2026).
AP1AR also shares sentences with these, for which no sentence is quoted: adenocarcinoma (1 paper); gliosarcoma (1).